PDLIM2 (PDZ and LIM domain 2)
Diseases named in the same sentence as PDLIM2 in open-access papers (continued):
Sharing a sentence is not in itself a finding about the gene and the disease.
lung carcinoma (continued). "Our mouse primary lung tumor and cell line studies indicated that PDLIM2 was also repressed in mouse lung cancer cells from different mouse models and mouse strains, suggesting that PDLIM2 repression is a common phenomenon of human and mouse lung cancers." (PMID 31757943, 2019). "The low expression of PDLIM2 in lung cancer promotes the malignant progression of tumors, and the mechanism may be related to mitochondrial dysfunction and tumor metabolite accumulation caused by the increase of mitochondrial reactive oxygen species (ROS)." (PMID 40476213, 2025). "PDLIM2 plays a tumor suppressive role in breast cancer, colorectal cancer, lung cancer, lymphatic cancer, kidney renal papillary cell carcinoma (KIRP) and ovarian cancer, while it is highly expressed in primary tumor tissues of metastatic kidney cancer, prostate cancer, meningioma, and schwannoma." (PMID 40476213, 2025). "Interestingly, ROS inhibitors can restore PDLIM2 expression in lung macrophages and prevents lung cancer in vivo." (PMID 41346604, 2025). "Therefore, maintaining normal expression levels of PDLIM2 is crucial for suppressing the onset and progression of lung cancer." (PMID 40476213, 2025). "Furthermore, delivery of exogenous PDLIM2 by clinically feasible nanoparticles shows high therapeutic efficacy in the mouse model of refractory lung cancer." (PMID 41346604, 2025). "Considering that PDLIM2 expression is affected in a larger range of cell types in infectious diseases compared to lung cancer, nanoPDLIM2 or other PDLIM2-targeted therapies may offer even better efficacy and safety for patients with infectious diseases." (PMID 41000764, 2025). "In summary, these findings suggest that HIF-1α is negatively regulated by PDLIM2 in lung cancer." (PMID 38880883, 2024). "Thus, PDLIM2 nanotherapy improves the therapeutic efficacy of chemotherapy through blocking both intrinsic and acquired chemoresistance of lung cancer cells." (PMID 39718207, 2024). "Using an authentic mouse model of lung cancer, we show, for the first time, that PDLIM2 nanotherapy shows efficacy and high safety, and more importantly, induces complete remission of all lung tumors in most animals when it is combined with anti-PD-1 and chemotherapeutic drugs." (PMID 39718207, 2024). "Importantly, combination with nanoPDLIM2 further significantly decreased both tumor number and tumor burden, suggesting a promising synergy between PDLIM2 nanotherapy and chemotherapy in lung cancer treatment." (PMID 39718207, 2024). "Notably, tumors derived from PDLIM2-knockdown lung cancer cells exhibited an accelerated growth rate and increased expression of inflammation cytokines controlled by NF-κB." (PMID 38880883, 2024). "In summary, the presented data identify genetic deletions as a major mechanism other than epigenetic alterations for PDLIM2 repression in human lung cancer, and PDLIM2 as a haploinsufficient tumor suppressor particularly important for suppressing lung cancer and therapy resistance." (PMID 39718207, 2024). "It remains unclear how PDLIM2 production is repressed in lung cancer: it is possible that cancer cells may acquire genetic alterations that affect PDLIM2 production, or there may be other changes to the structure of the DNA known as epigenetic changes." (PMID 39718207, 2024). "In this study, we examined whether and how PDLIM2 can be targeted to treat lung cancer in a faithful mouse model of human lung cancer." (PMID 39718207, 2024). "The results revealed an increased population of dysfunctional mitochondria (MitoTracker Green-positive, MitoTracker Red-negative) in PDLIM2-deficient lung cancer cells." (PMID 38880883, 2024). "We also examined whether PDLIM2 repression in human lung cancer involves genetic deletion and its relationship with epigenetic silencing." (PMID 39718207, 2024). "Similarly, results from TissueScan lung cancer cDNA arrays indicated downregulation of PDLIM2 expression in tumor tissues from stages I to IV patients." (PMID 38880883, 2024).
lung carcinoma (continued). "We observed a significant downregulation of PDLIM2 expression in lung cancer." (PMID 38880883, 2024). "PDLIM2 repression in AMs is thus both clinically and pathogenically relevant to lung cancer." (PMID 33539325, 2021). "In this regard, we have demonstrated that through promoting the ubiquitination and proteasomal degradation of nuclear STAT3 and RelA, the PDZ-LIM domain–containing protein PDLIM2 functions as a tumor suppressor particularly important for lung cancer suppression." (PMID 33539325, 2021). "Of note, the low PDLIM2 expression correlated with poor survival of patients with lung cancer." (PMID 33539325, 2021). "Conversely, PDLIM2 reconstitution crippled in vitro the growth, migration and invasion ability and suppressed in vivo the tumor formation and metastasis of human and mouse lung cancer cell lines." (PMID 31757943, 2019). "More importantly, MHC-I, like PDLIM2, is repressed in lung cancer." (PMID 31757943, 2019). "Notably, specific deletion of lung cancer PDLIM2 completely nullifies the anti-lung cancer effect of epigenetic therapy, suggesting a pivotal role of PDLIM2 restoration in this potentially new lung cancer therapy." (PMID 31757943, 2019). "Thus, PDLIM2 repression in lung cancer involves its promoter methylation by DNMTs and de-acetylation by HDACs." (PMID 31757943, 2019). "Taken together, these data suggested that PDLIM2 repression contributes to lung cancer immune evasion via repressing MHC-I expression/tumor antigen presentation and T-cell activation to evade CTLs on one hand, and inducing cell growth-related genes to resist CTL cytotoxicity on the other hand." (PMID 31757943, 2019). "In line with their ability in restoring PDLIM2 expression in lung cancer cells, epigenetic drugs 5-aza-dC and MS-275 could increase MHC-I expression in both mouse and human lung cancer cells." (PMID 31757943, 2019). "PDLIM2 epigenetic restoration or ectopic expression shows antitumor activity, and synergizes with anti-PD-1, notably, with chemotherapy for complete remission of most lung cancers." (PMID 31757943, 2019). "Our analysis revealed that lung cancer patients with high PDLIM2 expression and received AT showed better overall survival and recurrence-free survival compared to those patients with low PDLIM2 expression and received AT, and those patients with high PDLIM2 expression but did not receive AT." (PMID 31757943, 2019). "Overall, our data demonstrate PDLIM2 epigenetic repression and RelA/STAT3 regulation of MHC-I, MDR1 and cancer-related genes as a previously unknown mechanism underlying lung cancer development and resistance to PD-1 blockade and chemotherapy." (PMID 31757943, 2019). "Accordingly, PDLIM2 deletion from lung tumor cells diminished pulmonary T-cell activation in urethane mouse model of lung cancer, whereas re-expression of PDLIM2 in lung cancer cells increased tumor infiltration and activation of T cells and dendritic cells in syngeneic mouse model of lung cancer." (PMID 31757943, 2019). "We then examined whether PDLIM2 suppresses lung cancer through repressing the transcription factors NF-κB RelA and/or STAT3." (PMID 31757943, 2019). "Ectopic expression of PDLIM2 reverses the malignant phenotypes of lung cancer, and epigenetic agents, which can restore PDLIM2 expression, synergize with anti-PD-1 and notably with chemotherapeutic drugs for almost complete remission of lung cancer in the preclinical mouse model." (PMID 31757943, 2019). "Remarkably, clinically feasible nano-delivery of PDLIM2 (nanoPDLIM2) shows a promising efficacy as a monotherapy, and in combination with ICIs and chemo drugs, completely eradicates all tumors in most animals without adding toxicity, in the preclinical model of refractory lung cancer." (PMID 41346604, 2025).
lung carcinoma (continued). "Furthermore, they highlight the potential of PDLIM2 as a therapeutic target for the prevention and treatment of infectious diseases, especially given the high therapeutic efficacy and safety profile of nanoPDLIM2 in lung cancer models." (PMID 41000764, 2025). "More importantly, loss of PDLIM2 in lung tumors contributes to immune evasion, reduced MHC-I expression, increased chemoresistance, and activation of survival pathways, including upregulation of multidrug resistance genes like MDR1, promoting lung cancer and its therapy resistance." (PMID 40948895, 2025). "Given the role of PDLIM2 in inhibiting the expression of cell survival and proliferation genes in tumor cells, which contribute to chemoresistance, we tested whether nanoPDLIM2 increases the efficacy of chemotherapy in the mouse model of lung cancer." (PMID 39718207, 2024). "Additionally, they provide new insights into a strategy for precise targeted treatment by suggesting that HIF-1α inhibitors may serve as therapy for lung cancer patients with PDLIM2 downregulation." (PMID 38880883, 2024). "However, in our study, PDLIM2 led to different prognoses in different types of lung cancer." (PMID 35121770, 2022). "Thus, the expression of PDLIM2 was repressed in AMs in the mouse model of lung cancer." (PMID 33539325, 2021). "To investigate whether PDLIM2 is involved in lung cancer therapeutic responses, we analyzed the 100 patients with known adjuvant treatment (AT) information (divided to 50/50 for PDLIM2 high/low, 96 of them with known information for recurrence-free survival) in the lung cancer cohort GSE3774548." (PMID 31757943, 2019). "Besides lung cancer, PDLIM2 was repressed in many other cancers." (PMID 31757943, 2019). "Consistently, a significant decrease in PDLIM2 expression (<40% of the level in matched normal controls) was found in 28 out of 36 (based on the RNA level) and 51 out of 69 (based on the protein level) of our lung cancer samples directly isolated from patients." (PMID 31757943, 2019). "Notably, PDLIM2 restoration by nano-delivery of exogenous PDLIM2 (nanoPDLIM2) or pharmacological induction of endogenous PDLIM2 shows promising therapeutic activities and improves the efficacy of chemotherapy and immunotherapy in the mouse models of lung cancer." (PMID 41000764, 2025). "In the current study, we observed increased NF-κB activity in PDLIM2 knockdown LLC and A549 lung cancer cells." (PMID 38880883, 2024). "Therefore, we also investigated whether PDLIM2 regulates the HIF-1α expression in lung cancer." (PMID 38880883, 2024). "Our data also identified PDLIM2 downregulation in AMs and monocytes by ROS-activated BACH1 to increase STAT3 activation as a mechanism driving these immune cells to promote lung cancer." (PMID 33539325, 2021). "To further validate and expand these studies, we tried to define the mechanism by which PDLIM2/STAT3 signaling controls the pulmonary recruitment of blood monocytes, the prerequisite for AM expansion and lung cancer promotion." (PMID 33539325, 2021). "The expression of PDLIM2 and HIF-1α was reversely correlated in lung cancer patients." (PMID 38880883, 2024). "Additionally, analyzing the TCGA dataset using cBioportal for cancer genomics showed a reverse correlation between PDLIM2 and HIF-1α in lung cancer." (PMID 38880883, 2024). "Based on the findings above, we hypothesized that through restoring PDLIM2 expression to repress RelA and STAT3 activation, epigenetic drugs render lung cancer vulnerable to chemotherapeutic drugs and anti-PD-1." (PMID 31757943, 2019). "Additionally, PDLIM2 degrades STAT3 and the intranuclear transcription factor RelA (p65) through the ubiquitination-proteasome pathway, which exerts a cancer-inhibiting effect and thus inhibits the pathological process of lung cancer." (PMID 40476213, 2025).
lung carcinoma (continued). "Furthermore, the absence of PDLIM2 significantly augments the malignant behavior of NSCLC cells, and reduced expression levels are associated with poor patient survival in lung cancer." (PMID 40476213, 2025). "This funding suggesting PDLIM2 downregulation may serve as a potential marker for therapy with HIF-1 inhibitors, providing new insights into strategies for precise targeted treatment for lung cancer patients with PDLIM2 downregulation." (PMID 38880883, 2024). "Although reversal of PDLIM2 epigenetic repression by epigenetic drugs to restore PDLIM2 expression in cancer cells may be used to treat lung cancer, it is logical that this approach cannot be applied to lung tumors involving PDLIM2 LOH, which accounts for about 58% of all lung cancer cases." (PMID 39718207, 2024). "PDLIM2 downregulation leads to constitutive activation of the transcription factor STAT3, driving AM protumorigenic polarization/activation and differentiation from monocytes attracted from the circulation to suppress cytotoxic T lymphocytes and promote lung cancer." (PMID 33539325, 2021). "However, the pathophysiological significance of these findings and in particular the role of PDLIM2 in lung cancer has not been studied." (PMID 31757943, 2019).
prostate carcinoma (10 papers, 2016 to 2024). A carcinoma that arises from epithelial cells of the prostate gland. "In prostate cancer, patients with a high expression of PDLIM2 had a poor prognosis, and PDLIM2 was correlated with EMT and immune cell infiltration by acting as an oncogene." (PMID 36901953, 2023). "Another study showed that PDLIM2 inhibition effectively reduced the tumor growth and invasiveness of human castration-resistant prostate cancer cells." (PMID 35121770, 2022). "PDLIM2 suppression efficiently reduces tumor growth and invasiveness of human castration-resistant prostate cancer-like cells." (PMID 34713769, 2022). "The expression level of PDLIM2 in androgen-sensitive prostate cancer cells and CRPC-like cells was significantly different, and PDLIM2 was expressed at a high level in CRPC-like cells." (PMID 34203785, 2021). "In a previous study, we found PDLIM2 to be expressed at higher levels in castration-resistant prostate cancer (CRPC)-like cells in prostate cancer." (PMID 34203785, 2021). "However, in prostate cancer (PC) and GC, PDLIM2 plays a pro-carcinogenic role, and specific deletion of PDLIM2 significantly suppressed cell proliferation and migration." (PMID 37894409, 2023). "The inhibition of PDLIM2 resulted in a reduced number and weakened viability, proliferation, and clonal growth of prostate cancer cells; furthermore, PDLIM2 may play a carcinogenic role in human CRPC-like cells." (PMID 34203785, 2021). "This prediction appears to be based largely on the results of one previous investigation into PDLIM2-modulated gene expression in DU145 prostate carcinoma cells and the direction of expression change of about half the genes in that study is different from that in ours." (PMID 27144453, 2016). "However, higher expression of PDLIM2 has also been observed in certain cancer types, such as triple-negative breast cancer, esophageal squamous cell carcinoma, acute myeloid leukemia, and prostate cancer, where it has been suggested as a prognostic marker." (PMID 38880883, 2024). "In addition, PDLIM2 suppression efficiently reduces tumor growth of prostate cancer-like cells." (PMID 34713769, 2022). "The high expression of PDZ and LIM domain 2 (PDLIM2), a member of ALP, was also correlated with infiltrating immune cells and predicted poor prognoses in patients with prostate cancer." (PMID 36901953, 2023). "PDLIM2, Fbw7, and constitutive photomorphogenic 1 (COP1) were identified as E3 ligases for STAT3 in T helper 17 cells, diffuse large B-cell lymphoma (DLBCL) cells, and prostate cancer cells, and several proteins, including TMF/ARA160, are involved in proteasomal STAT3 degradation." (PMID 33859351, 2021).
breast carcinoma (7 papers, 2011 to 2025). "Analysis of METABRIC and TCGA breast cancer datasets via immune deconvolution methods further demonstrated an association of PDLIM2 mRNA and protein expression with M2 macrophage infiltration." (PMID 36531051, 2022). "The observations from breast cancer TMAs were supported by cellular deconvolution analyses of METABRIC and TCGA-BRCA gene expression datasets, suggesting that PDLIM2 is generally associated with M2 macrophages in breast cancer." (PMID 36531051, 2022). "We previously reported that PDLIM2 expression was elevated in TNBC compared with other breast cancers or normal breast tissue, and that this was associated with amplified cell adhesion and beta catenin signalling." (PMID 36531051, 2022). "The findings thus far indicated that PDLIM2 is associated with the M2 macrophage subset in breast cancers, including TNBC, and is required for the full adoption of the M2 phenotype in mouse BMDM." (PMID 36531051, 2022). "In breast cancer, PDLIM2 was associated with adhesion signaling and β-catenin activity; the inhibition of PDLIM2 plays a role in inhibiting tumor growth." (PMID 34203785, 2021). "Moreover, PDLIM2 is commonly associated with M2 macrophages in breast cancer and is required for their migration." (PMID 40476213, 2025). "Our findings demonstrate that high PDLIM2 expression in breast cancer is predominantly associated with higher levels of CD163- and CD206-positive macrophages that likely represent the M2 subset, whereas the expression of T lymphocytic markers is not uniquely associated with PDLIM2 expression." (PMID 36531051, 2022). "Finally, analysis of publicly available breast cancer datasets showed that high PDLIM2 expression is associated with increased M2 macrophage infiltration." (PMID 36531051, 2022). "In summary, we conclude that PDLIM2 is required for the migratory capacity of macrophages and full adoption of the M2 phenotype, and that high levels of PDLIM2 in breast cancer tumour and stroma is associated with pro-tumorigenic M2 macrophage activity, particularly in TNBC." (PMID 36531051, 2022). "To address this further, we interrogated the high expression of PDLIM2 that was observed in the stroma of this breast cancer cohort." (PMID 36531051, 2022). "We previously observed in a breast cancer TMA cohort that PDLIM2 is expressed in 40-60% of the infiltrating stroma of tumours." (PMID 36531051, 2022). "We previously reported that PDLIM2 is more highly expressed in Triple Negative Breast Cancer (TNBC) than in other breast cancer types or normal breast tissue." (PMID 36531051, 2022). "Since PDLIM2 is significantly more highly expressed in TNBC than in other breast cancer types, we analyzed the phenotype of macrophages present in TNBC cores." (PMID 36531051, 2022). "Consistently, upregulated exosomal miR-222 was reported to downregulate PDLIM2 tumor suppressor and to activate NF-κB, which results in lymph node metastasis in advanced breast cancer." (PMID 33901254, 2021). "Several PDZ domain-containing proteins were identified that interact with the PDZ-binding motif of Claudin-2 in liver metastatic breast cancer cells, including Afadin, Arhgap21, Pdlim2, Pdlim7, Rims2, Scrib, and ZO-1." (PMID 30692208, 2019). "PDZ-LIM domain-containing protein 2 (PDLIM2) contains a tumor suppression function and has been shown to be repressed in breast cancer cells." (PMID 21845090, 2011). "The treatment of breast cancer cells with 5-aza-2′-deoxycytidine reversed the methylation of the PDLIM2 promoter, restored PDLIM2 expression, and suppressed tumorigenicity of human breast cancer cells." (PMID 21845090, 2011). "In addition, miR-222 can over activate the NF-κB signaling pathway in breast cancer cells by downregulating PDLIM2 expression, leading to increased tumorigenicity in breast cancer cells." (PMID 40476213, 2025). "However, CD206 was expressed at significantly higher levels in the stroma of breast cancers where the tumour cells also expressed PDLIM2." (PMID 36531051, 2022).